MALAT1 (metastasis associated lung adenocarcinoma transcript 1)
Diseases named in the same sentence as MALAT1 in open-access papers (continued):
Sharing a sentence is not in itself a finding about the gene and the disease.
infarction (6 papers, 2020 to 2023). A localised pathological necrosis of tissue resulting from obstruction of the blood supply usually by a thrombus, an embolus, or vascular torsion. "Moreover, downregulation of lncRNA metastasis-associated lung adenocarcinoma transcript 1 (MALAT1) and myocardial infarction associated transcript (MIAT) improved DCM by reducing apoptosis and ameliorating cardiac function." (PMID 33537003, 2020). "Silencing of MALAT1 using MALAT1‐locked nucleic acid GapmeR significantly attenuated KLF2 and CD31 protein expression after infarction induced by HBO‐induced exosomes." (PMID 32939962, 2020).
laryngeal carcinoma (6 papers, 2016 to 2025). Carcinoma that arises from the laryngeal epithelium. "Although MALAT1 has been investigated in multiple human cancers, it is rarely known whether it is associated with laryngeal cancer development in some mechanisms." (PMID 31792655, 2020). "Our data also show a hint that the expression level of MALAT1 may be linked to clinical stages of laryngeal cancer." (PMID 31792655, 2020). "Metastasis-associated lung adenocarcinoma transcript 1 (MALAT1) is a putative oncogenic lncRNA of more than 8000 nt transcribed from chromosome 11q13.1, and overexpressed in several solid tumors including lung, colorectal, bladder and laryngeal cancers." (PMID 27177333, 2016). "Our results demonstrated that down-regulating MALAT1 can induce increased laryngeal cancer cell apoptosis and inhibition of cell proliferation." (PMID 31792655, 2020). "In our study when depleting MALAT1 in laryngeal cancer cell lines, the invasion and migration of both laryngeal cancer cell lines Hep-2 and hypopharyngeal cancer cell FaDu were inhibited." (PMID 31792655, 2020). "Recent researches have proved that MALAT1 was overexpressed and oncogenic in some tumors, including lung, colorectal, bladder and laryngeal cancers." (PMID 30787203, 2019). "Recent studies have identified that MALAT1 was overexpressed and oncogenic in some tumors, including lung, colorectal, bladder and laryngeal cancers." (PMID 30787203, 2019). "Moreover, we developed a MALAT1 silencing model in human laryngeal tumor cells by transfecting MALAT1 small interfering RNA into human laryngeal carcinoma cell line Hep-2 and pharyngeal carcinoma cell line FaDu with Lipofectamine 2000 system." (PMID 31792655, 2020). "We detected the expression of MALAT1 in laryngeal cancer tissues and hypopharyngeal cancer tissues." (PMID 31792655, 2020). "Although due to the limited number of cases in this study, the association between MALAT1 expression and clinical staging of laryngeal cancer could not be confirmed, our result still shows the trend that the more advanced the stage, the higher the MALAT1 expression level will be." (PMID 31792655, 2020). "Our study is a pilot study, which is also not sufficient to elucidate the complicated role of MALAT1 in tumorigenesis and progression of laryngeal cancer." (PMID 31792655, 2020). "The ISH data illustrated that MALAT1 expression was significantly increased in laryngeal cancer and hypopharyngeal tissues as compared with that in the normal tissues (P < 0.05)." (PMID 31792655, 2020).
liver cirrhosis (6 papers, 2018 to 2026). "Among 130 patients with liver cirrhosis, high MALAT1 expression was associated with significantly shorter OS than low expression (p = 0.018) and with a tendency toward shorter PFS (p = 0.0566)." (PMID 36685103, 2022). "Additionally, MALAT1 expression level was significantly associated with liver cirrhosis, vascular invasion, and tumor capsular infiltration (p < 0.05 for all)." (PMID 36685103, 2022). "A recent study reported that serum MALAT1 levels could differentiate HCC patients (N = 30) from HCV-induced liver cirrhosis patients (N = 20) and healthy controls (N = 20)." (PMID 30134610, 2018). "Next, to clarify the effects of MALAT1 genetic polymorphisms on the HCC clinicopathological status, including clinical stage, primary tumor size, lymph node and distant metastasis, vascular invasion, Child–Pugh grade, hepatitis virus infection, and liver cirrhosis." (PMID 31500187, 2019). "Levels of MALAT1 and RAC1 were increased 6.8-fold and 84%, respectively, in patients with liver cirrhosis of undisclosed etiology, suggesting that the same network may play a role in human fibrosis." (PMID 30134610, 2018).
systemic lupus erythematosus (6 papers, 2020 to 2022). An autoimmune multi-organ disease typically associated with vasculopathy and autoantibody production. "lncRNA MALAT1 has been identified to be a novel inflammatory regulator in autoimmune and inflammatory diseases such as human systemic lupus erythematosus." (PMID 31830649, 2020). "MALAT1 is also an inflammatory regulator in human systemic lupus erythematosus." (PMID 33134293, 2020). "MALAT1 expression is upregulated in monocytes of immune disease models [e.g., systemic lupus erythematosus (SLE)]." (PMID 35359568, 2022). "Similarly to MS, analysis of PBMCs, T cells, B cells, and monocytes from 36 Chinese patients with systemic lupus erythematosus compared with 45 healthy controls revealed that MALAT1 expression was abnormally increased in the SLE patients, with predominant overexpression in monocytes." (PMID 35796900, 2022).
uveal melanoma (6 papers, 2018 to 2025). A melanoma derived from melanocytes of the uveal tract. "In vitro studies indicate that the combination of ART and verteporfin significantly increases apoptosis rates in human uveal melanoma cells by regulating the MALAT1/miR-218/YAP signaling axis." (PMID 41160271, 2025). "Previous study reported that MALAT1 increased cell migration via modulating miR-140 expression in a uveal melanoma cell line." (PMID 32342982, 2020). "miRNA-140-3p was reported to be regulated by MALAT1 in uveal melanoma cells." (PMID 32993558, 2020). "In addition, it has been shown that the down-regulation function of MALAT1 restrain the development of uveal melanoma via inhibition of HOXC4." (PMID 33392203, 2020).
abdominal aortic aneurysm (5 papers, 2020 to 2023). Enlargement and ballooning of the vessel that supplies arterial blood to the abdomen, pelvis and legs. "LncRNA-MALAT1 inhibitor, MALAT1-IN-1, can protect the aorta by preventing, inhibiting, and reversing abdominal aortic aneurysms based on three aspects." (PMID 36903369, 2023). "Malat1 knockout reduced MMPs and inflammatory factor production induced by Ang II in smooth muscle cells, and the Malat1 inhibitor exerted preventive, inhibitory, and reversing effects on AngII-induced abdominal aortic aneurysm (AAA) in vivo revealed by a series of animal experiments." (PMID 35473929, 2022). "Previous studies have demonstrated that in human abdominal aortic aneurysms, IL6 increased NOX activity and MALAT1 expression in a time-dependent manner, leading to excessive ROS production." (PMID 35692503, 2022). "In human abdominal aortic aneurysm, IL-6 induced the activity of NOX2 in the aortic endothelial cells via the induction of the lncRNA MALAT1 by an ERK-dependent mechanism." (PMID 32929606, 2020). "In addition, relevant experiments accurately identified the MALAT1 inhibitor, a therapeutic agent targeting lncRNA-MALAT, and for the first time, the rationale for the application of this inhibitor in the prevention and treatment of abdominal aortic aneurysms was discovered." (PMID 36903369, 2023).
acute pancreatitis (5 papers, 2021 to 2025). An acute inflammatory process that leads to necrosis of the pancreatic parenchyma. "In acute pancreatitis, Metastasis-associated lung adenocarcinoma transcript-1 (MALAT1) embedded in EVs competitively binds to miR-181a-5p and induces M1 macrophages, further regulating high mobility group box protein-1 (HMGB1)-TLR4 signaling pathway, thereby upregulating TNF-α and IL-6 levels." (PMID 37237557, 2023). "Indeed, higher MALAT1 expression is associated with inflammation in acute pancreatitis." (PMID 37860007, 2023). "MALAT1, with high expression in severe acute pancreatitis patients’ plasma and corresponding mouse models, plays a critical role in this condition." (PMID 38473915, 2024). "Additionally, MALAT1 is found in serum EVs of acute pancreatitis patients, stimulating macrophages to activate TLR4/NF-κB signaling and M1 polarization via the miR-181a-5p/HMGB1 axis." (PMID 38473915, 2024).
brain infarct (5 papers, 2020 to 2025). "Moreover, Malat1 KO mice appeared larger cerebral infarct size, worsened neurological deficit, and weaken sensorimotor functions." (PMID 35677353, 2022). "MALAT1 increases the release of inflammatory cytokines by inhibiting the ERK/MAPK signaling pathway, which upregulates neuronal apoptosis and aggravates brain damage after cerebral infarction in rats." (PMID 33192306, 2020).
cardiomyopathy (5 papers, 2018 to 2024). A disease of the heart muscle or myocardium proper. "In the rat cardiomyopathy of T1DM induced by streptozotocin, MALAT1 in myocardial tissues was up-regulated." (PMID 30342478, 2018). "Like MALAT1, the expression of cardiac MIAT was significantly upregulated in Sprague-Dawley rats with the cardiomyopathy of T1DM." (PMID 30342478, 2018).
cerebrovascular diseases (5 papers, 2020 to 2023). "Previous studies revealed that the MALAT1 gene polymorphism was associated with cardiac and cerebrovascular diseases." (PMID 35392816, 2022). "The protective roles of lncRNA Malat1 in cerebrovascular diseases have been reportedthroughactivating phosphatidylinositol 3-kinase (PI3K) viainhibition of pro-apoptotic or pro-inflammatory factors." (PMID 38974129, 2023). "As to its role in neurological diseases or cerebrovascular diseases, previous studies demonstrate that lnc-MALAT1 presents protective effects in these diseases via repressing pro-apoptotic or pro-inflammatory factors." (PMID 33111743, 2020). "Meanwhile, lnc-MALAT1 has been reported to be downregulated and primarily play an anti-inflammatory role in patients with neurological disease as well as with cardiovascular and cerebrovascular disease." (PMID 33111743, 2020). "Previous clinical trials focus mainly on the exploration of lnc-MALAT1 in cancer patients, showing that lnc-MALAT1 plays a tumor-promotive role, while information about the role of lnc-MALAT1 in neurological diseases or cerebrovascular diseases is still limited (22, –24)." (PMID 33111743, 2020).
Cervical Tumor (5 papers, 2021 to 2025). "Gain- or loss-of-function analyses in cervical tumor cells have further verified the regulatory role of MALAT1 on miR-124." (PMID 34221014, 2021). "Thus, our study was designed to investigate the underlying mechanism of LncRNA MALAT1 on cervical tumor cell proliferation." (PMID 34221014, 2021). "Findings from prior studies indicate that dysregulated lncRNAs, such as HOTAIR and MALAT1, promote cervical tumor progression and metastasis." (PMID 41300873, 2025). "To further underpin the effect of the LncRNA MALAT1/miR-124 axis on cervical tumor growth, we used tumor-bearing mice with tumor tissue index and survival rate." (PMID 34221014, 2021). "Second, a significant alternation of MALAT1/miR-124 axis was found in the proliferation of cervical tumor cells, suggesting the regulatory role of the MALAT1/miR-124 axis on cell proliferation." (PMID 34221014, 2021). "The result showed that LncRNA MALAT1 was highly expressed in carcinoma tissues and cervical tumor cells." (PMID 34221014, 2021). "We observed that miR-124 was the potential target of LncRNA MALAT1 in cervical tumor cell lines (Hela, C-33A, Caski, and SiHa), the expression level of which is negatively correlated with LncRNA MALAT1 in cervical tumor cells, tissues of cervical patients, and mice." (PMID 34221014, 2021). "According to the sequence examined and previous studies, we hypothesized that miR-124 was the potential target of MALAT1 in regulating cervical tumor progression." (PMID 34221014, 2021). "Here, we hypothesized that MALAT1 is the key mediator for the proliferation of cervical tumor cells by its potential target, miR-124, increasing the tumor growth, as well to accelerate the development during NSCLC." (PMID 34221014, 2021). "First, we revealed the negative correlation between MALAT1 and miR-124 in cervical tumor tissues and cell lines, verifying their regulatory relationship." (PMID 34221014, 2021). "Additionally, we observed that the LncRNA MALAT1/miR-124 axis failed to regulate the proliferation in End/E6E cells confirming the regulatory axis of LncRNA MALAT1/miR-124 on cervical tumor cell proliferation." (PMID 34221014, 2021).
cholangiocarcinoma (5 papers, 2017 to 2025). A carcinoma that arises from the intrahepatic biliary tree (intrahepatic cholangiocarcinoma) or from the junction, or adjacent to the junction, of the right and left hepatic ducts (hilar cholangiocarcinoma). "This indicates that MALAT-1 promotes cholangiocarcinoma cell invasion and metastasis by modulating EMT-related proteins." (PMID 38201661, 2024). "Silencing MALAT-1 downregulates the phosphorylated level of PI3Kand Akt, while the total protein level remains the same, indicating that MALAT-1 may modulate cholangiocarcinoma cell migration and invasion by activating the PI3K/Akt signaling pathway." (PMID 38201661, 2024). "In CCA especially hilar cholangiocarcinoma (HCCA), the expression level of MALAT1 is much higher than paracancerous tissue." (PMID 29246025, 2017).
chronic myeloid leukemia (5 papers, 2021 to 2024). "And lncRNA MALAT1 was demonstrated to promote the proliferation of chronic myeloid leukemia cells via modulating miR-328." (PMID 36934373, 2023). "In another study, MALAT1 promoted the proliferation and imatinib resistance of chronic myeloid leukemia cells via the MALAT1/miR-328 axis." (PMID 33726486, 2021). "In addition, MALAT1 silencing greatly blocked the cell cycle of chronic myeloid leukemia (CML) cells and inhibited cell proliferation by releasing the sponging effect on miR-328, which attenuated the chemotherapy resistance of CML cells to imatinib." (PMID 36829256, 2023). "Also, lncRNA MALAT1 was demonstrated to promote the proliferation of chronic myeloid leukemia cells via modulating miR-328." (PMID 36934373, 2023).
deep vein thrombosis (5 papers, 2021 to 2023). "Furthermore, MALAT1 alleviated deep vein thrombosis (DVT) by inhibiting the proliferation and migration of endothelial progenitor cells (EPCs) and involved in thrombosis dissolution via regulating the Wnt/β-catenin signaling pathway." (PMID 34408749, 2021). "It is also interesting to note that MALAT1 negatively regulates proliferation and migration of endothelial progenitor cells in deep vein thrombosis (DVT)." (PMID 36466827, 2022). "In addition, MALAT1 inhibited deep vein thrombosis (DVT) by inactivating the proliferation and migration of endothelial progenitor cells (EPCs) and was involved in thrombus dissolution through regulation of the Wnt/b-catenin signaling pathway." (PMID 36852336, 2023).
depression (5 papers, 2019 to 2025). "The experimental results were consistent with the prediction, indicating that Malat1 in oligodendrocytes at different developmental stages in the PFC is associated with the occurrence of depression; however, the specific mechanism needs to be further studied." (PMID 38281050, 2024). "The lncRNAs HOTAIR and MALAT1 are dysregulated in depression and have been implicated in the modulation of gene expression and cellular processes relevant to depression." (PMID 39194576, 2024). "The lncRNAs VLDLR-AS1 and MALAT1 changed significantly (p < 0.05) with respect to the depression levels." (PMID 38338752, 2024). "A secondary analysis of clinical data from LIMBIC CENC was conducted to evaluate the psychological symptom burden, and the results show that lncRNAs VLDLR-AS1 and MALAT1 are correlated with symptoms of depression." (PMID 38338752, 2024). "In addition, results of fluorescence in situ hybridization assay showed that Malat1 plays a critical role in the occurrence of depression." (PMID 38281050, 2024). "Finally, the levels of lncRNAs VLDLR-AS1, NEAT1, GAS5 and MALAT1 were analyzed for correlation with depression symptoms, measured using the Patient Health Questionnaire-9 (PHQ-9)." (PMID 38338752, 2024). "In view of the high ranking of MALAT1, we hypothesized that MALAT1 may play an important role in the development of depression and selected it as a follow-up verification object." (PMID 38281050, 2024). "MALAT1 has been widely studied in cancer, but little is known about its role in depression." (PMID 38281050, 2024). "The results demonstrate that the initiation developmental stage of the OL was a better predictor of the occurrence of depression than other developmental stages, and that the lncRNA Malat1 might be closely related to the occurrence of depression." (PMID 38281050, 2024). "Additionally, lncRNA VLDLR-AS1 and MALAT1 levels are correlated to depression states in the participants." (PMID 38338752, 2024). "Currently, there are few reports on the relationship between MALAT1 and depression." (PMID 38281050, 2024). "Through comparison with the top-ranked candidate genes and subsequent FISH assay, we revealed that lncRNA Malat1 might be closely related to the occurrence of depression." (PMID 38281050, 2024). "Our finding suggests that the serum lncRNA levels of VLDLR-AS1 and MALAT1 may provide a measurable, quantitative tool to screen for depression." (PMID 38338752, 2024). "In addition, brain samples from patients with depression are limited and extremely difficult to collect, and therefore, we verified the candidate gene Malat1 in animal models." (PMID 38281050, 2024). "Interestingly, the levels of VLDLR-AS1, along with MALAT1, were correlated with depression in the participants." (PMID 38338752, 2024). "We conducted a secondary analysis of the psychological symptom burden in the LIMBIC CENC cohort to evaluate whether the levels of the four serum lncRNAs (VLDLR-AS1, MALAT1, NEAT1, GAS5) correlate to symptom burden (such as cognition, memory, depression or PTSD) after rmTBI." (PMID 38338752, 2024).
epilepsy (5 papers, 2013 to 2022). A brain disorder characterized by episodes of abnormally increased neuronal discharge resulting in transient episodes of sensory or motor neurological dysfunction, or psychic dysfunction. "It is also noteworthy that MALAT1 can also bind to miR-101 to upregulate PI3K/AKT pathway in epilepsy." (PMID 35898503, 2022). "Regarding its role in epilepsy, some authors recently found that a downregulation of MALAT1 is able to inhibit excessive autophagy and the apoptosis of hippocampal neurons in a pilocarpine-induced epilepsy rat model by the activation of the PI3K/Akt signaling pathway." (PMID 31581735, 2019). "The authors demonstrated that MALAT1 was significantly augmented in the hippocampus of rats with epilepsy and that the injection of an antisense molecule (si-MALAT1) was efficient in reducing this level resulting in a more prolonged latency duration of epilepsy seizure." (PMID 31581735, 2019). "Taken together, these findings indicate that down-regulation of MALAT1 activates the PI3K/Akt signaling pathway to protect hippocampal neurons against autophagy and apoptosis in rats with epilepsy." (PMID 35328484, 2022).